HGF (hepatocyte growth factor)
Diseases named in the same sentence as HGF in open-access papers (continued):
Sharing a sentence is not in itself a finding about the gene and the disease.
tumor (continued). "This is an E. coli-derived humanized, affinity-matured antibody, which engages MET, thereby inhibiting HGF binding and receptor phosphorylation in HGF-dependent tumor models." (PMID 28018347, 2016). "HGF and its receptor c-Met play an important role in a series of complex intracellular pathways by specifically binding with each other to regulate tumor invasion, metastasis, and angiogenesis." (PMID 27069297, 2016). "High expressions of mRNA of HGF and MET in tumor tissues were also associated with poor prognosis in advanced GC patients who underwent gastrectomy." (PMID 26716644, 2016). "c-Met is a membrane receptor tyrosine kinase capable of binding to HGF and activating the HGF/c-Met signaling pathway, which thereby regulates the proliferation and migration of tumor cells." (PMID 26728266, 2016). "ABT-700 activity differs from the recently reported anti-c-Met antibody LY2875358 in tumor cells where c-Met signaling can be driven by both receptor expression and HGF stimulation." (PMID 26879245, 2016). "HGF is a major component of the OB-derived hematopoietic activity within the endosteal niche, and tumor cells typically localize close to the endosteum." (PMID 26934743, 2016). "Through activating the Met signaling pathway, HGF (also known as a scattering factor) modifies the tumor microenvironment to facilitate cancer progression." (PMID 27203677, 2016). "HGF is synthesized and secreted by tumor cells or by stromal cells, such as fibroblasts, as the inactive precursor, pro-HGF." (PMID 27121052, 2016). "In classical Hodgkin lymphoma (cHL), the expression of c-MET was detected in the tumor cells from 38 to 52% of the patients, and the expression of HGF was found in 8% of the patients." (PMID 27923392, 2016). "Using the same antibody in a separate study, HGF overexpression, in which ≥50% of tumor cells exhibited positive staining, was identified in 25% of 88 patients." (PMID 27013592, 2016). "For instance, HGF secreted by the TME can induce a more immature phenotype in differentiated intestinal tumor cells, including the expression of stem cell markers." (PMID 27308617, 2016). "Tumours with increased copy number in this cohort had a significantly higher S-phase fraction (SPF) than tumours with fewer HGF copies." (PMID 27175600, 2016). "Particularly, we have shown that several common features of the solid tumor microenvironment, hepatic growth factor (HGF), and acidic extracellular (pHe) trigger lysosome outward movement, accompanied by increased cathepsin B secretion and tumor cell invasion." (PMID 26784896, 2016). "Synergism to induce greater GBM tumor cell killing has been shown with the combination of hypofractionated ionizing radiation and SF/HGF/cMet blockade, via U1snRNA/ribozymes." (PMID 27043632, 2016). "The ability of the BpAb to affect HGF-independent MET activity in tumor cells displaying constitutive MET activation was investigated." (PMID 27546726, 2016). "The accumulation of information implicating c-Met as a major regulator of tumor progression and the prevalence of HGF/c-Met activation in human malignancies continue to drive the search for more effective c-Met inhibitors, since its first discovery in 1984." (PMID 27086914, 2016). "Another important function of HGF/c-Met axis activation is to promote cancer cells migration and invasion, which contribute to the tumor metastasis." (PMID 27191264, 2016). "It was concluded from these studies that activation of the HGF/MET pathway in tumor tissue plays significant roles in tumor progression and prognosis of locally advanced GC." (PMID 26716644, 2016). "According to this study, MET-positivity by IHC in tumor tissues is considered a predictive marker for efficacy of anti-HGF antibody in metastatic GC patients." (PMID 26716644, 2016).
tumor (continued). "Comprehensive analysis for drug resistance conferred by the interaction between tumor cells and stromal cells has shown that HGF secreted from stromal cells confers resistance/survival in tumor cells against molecular-targeted agents." (PMID 27683122, 2016). "Met activation in tumor cells can occur through several molecular mechanisms, such as overexpression, structural alterations, and HGF-dependent or HGF-independent activation." (PMID 27494877, 2016). "In patients with stable disease past the first tumor assessment, median change from baseline HGF was +28.2% (std = 37.5, mean = 25.0, min = −96.6, max = 80.1) regardless of treatment." (PMID 27579536, 2016). "MET and HGF expression is significantly higher in BC cells than in adjacent non-tumor cells in surgical specimens." (PMID 27714541, 2016). "Another pathway HGF/c-MET/ETS-1 also plays a central role in tumor proliferation, invasion and metastasis." (PMID 27824903, 2016). "HGF/c-Met has also been shown to increase the secretion of pro-angiogenic factors by tumor cells, such as IL-8." (PMID 27191264, 2016). "Aberrant HGF-Met activation reportedly promotes tumor cell proliferation and metastasis via growth factor receptors and other oncogenic receptor pathways, and we found that sorafenib markedly inhibited HGF expression in polarized macrophages." (PMID 27203677, 2016). "MET‐pos‐NS were kept in a standard EGF/bFGF medium, supplied with HGF to better mimick the brain (tumor) microenvironment." (PMID 27138567, 2016). "HGF amplification was detected in 6% (11/205) and 7% (12/184) of the tumours, and copy gain in 21% (41/205) and 27% (50/184), in cohort 1 and 2, respectively." (PMID 27175600, 2016). "ABT-700 and parental mAb m224G11 blocked the HGF-induced c-Met phosphorylation of A549 tumor cell line with an IC50 of 1.0 nM." (PMID 26879245, 2016). "Gliomas have been shown to express high levels of TGF-β, VEGFA, HGF, and Sema3a, which promote tumor growth, neo-vascularization, invasiveness, and dispersal." (PMID 26755653, 2016). "In this study, patients with high level of HGF had shorter survival compared with those with low HGF by a log-rank test, and serum HGF also was had positively correlated with disease progression, stage and tumor metastasis." (PMID 26716644, 2016). "Tumor size increased 2-fold in rats that underwent 70% hepatectomy compared to sham operated animals with an increase of both HGF and H19 RNAs." (PMID 26623562, 2016). "Many stem cells including F3 NSCs have tumor- and lesion-tropic properties mediated by chemoattractants such as hepatocyte growth factor (HGF), stromal cell-derived factor-1 (SDF), vascular endothelial cell growth factor (VEGF), and stem cell factor (SCF)." (PMID 27429621, 2016). "HGF/c-Met pathway promotes angiogenesis, which is also an important process in tumor formation and metastasis." (PMID 27191264, 2016). "Tumor cell scattering in primary tumors is the first step in metastasis, and as its name implies, HGF/SF plays a pivotal role through the paracrine loop between HGF-producing stroma and MET-expressing tumor cells." (PMID 26623562, 2016). "As a pivotal oncogene for tumor progression influencing the HGF/c-MET pathway, MACC1, has been shown to participate in many biological mechanisms that produce poor clinical outcomes." (PMID 27581375, 2016). "To further evaluate the blocking effect of HS20 on HGF-dependent cell-cell interaction, we performeda tumor spheroid formation assay." (PMID 26332121, 2015). "Emerging evidence demonstrates that HSPGs interact with HGF through HS moieties in order to promote HGF-mediated signaling and subsequently tumor pathogenesis." (PMID 26332121, 2015). "Expression profiling of different cellular constituents of tumors indicated that HGF mRNA was predominantly expressed by CAFs and ECs while IL-6 mRNA was mainly expressed by tumor cells and by CAFs." (PMID 25849942, 2015).
tumor (continued). "Physiological doses of estrogen suppress HCC metastasis by decreasing interleukin-6 and hepatocyte growth factor expression in the tumor microenvironment." (PMID 26503703, 2015). "Among these signaling molecules, Hepatocyte Growth Factor (HGF) is released by many cell types of the tumor microenvironment to target its receptor c-MET within the cells of the primary tumor." (PMID 28536400, 2015). "On the other hand, HGF status was significantly correlated with tumor differentiation (P = 0.024), tumor depth (P = 0.028), lymph node metastasis (P = 0.014), and pathological stage (P = 0.022)." (PMID 26036285, 2015). "Mounting studies highlighted the essential role of the HGF/c-MET axis in driving HCC tumor progression." (PMID 25607934, 2015). "Activated HGF/c-MET signaling is reported to play an important role in tumor stromal-interactions under hypoxia." (PMID 28536400, 2015). "The status of HGF/c-Met signaling in 26 HCC tissue samples was evaluated by examining the amount of Tyr1234 phosphorylated c-Met (p-c-Met Tyr1234, the activated form of c-Met) coupled with HGF in the tumor environment." (PMID 25607934, 2015). "HGF is expressed and released from surrounding stromal and mesenchymal cells and acts in a paracrine manner on c-Met-expressing tumor cells." (PMID 25726528, 2015). "In conclusion, our study suggests that GPC3 is involved in tumor cell motility via HS chain-mediated coordination with the HGF/Met pathway." (PMID 26332121, 2015). "Previous studies showed that the HGF/c-Met pathway played a crucial role in tumor invasion and metastasis, and blocking the pathway suppressed tumor infiltration into neighboring tissues." (PMID 26191485, 2015). "Hepatocyte growth factor/scatter factor (HGF/SF) has been shown to play an important role in tumor migration and metastasis." (PMID 26448742, 2015). "Activation of the HGF/c-MET axis induces different phenotypes depending on tumor stage: inducing proliferation and angiogenesis in primary tumors, stimulating motility to form micrometastases, and regaining the proliferation phenotype to form overt metastases." (PMID 28536400, 2015). "It has been reported that some cell types in the tumor microenvironment such as stromal cells can secrete growth factors like hepatocyte growth factor (HGF) or tumor necrosis factor-α (TNF-α) resulting in resistance to BRAF inhibition." (PMID 25939769, 2015). "A recent report proposed an intriguing interaction between endoglin and HGF, showing that soluble endoglin inhibited baseline and HGF stimulated Met signalling, impairing proliferation, migration and invasion of spindle cells, in mouse tumour model." (PMID 26296972, 2015). "Foretinib inhibits HGF-induced c-Met phosphorylation, inhibits tumour cell growth in hypoxic and normoxic conditions, and has been shown to reduce tumour cell burden in an in vivo model of lung cancer." (PMID 25887320, 2015). "One recent study demonstrated Nox2-dependent ROS-JNK signaling is essential for HGF-induced mobilization of endothelial progenitor cells (EPCs), involved in proangiogenesis and tumor progression." (PMID 26416447, 2015). "To better understand the relationship between tumour microenvironment parameters and cell invasion, we studied the effects of HGF, EGF, IGF, netrin, PDGF-B, TNF-α, bFGF, IL-6, NGF, TGF-β and PlGF-1 in the 3D environment." (PMID 26486848, 2015). "This phenomenon, besides highlighting the importance of the tumor microenvironment, further confirms that fibroblast-derived HGF/c-MET signaling is involved in resistance to chemotherapy reagents." (PMID 26090722, 2015). "For both liver regeneration and spontaneous HCC development, there is an inclusive requirement for MET expression, and when HGF induces autocrine activation, the tumor displays sensitivity to a small-molecule MET inhibitor." (PMID 28536405, 2015). "Blocking of HGF/SF with heparin and a neutralizing HGF antibody resulted in reduced tumor burden due to decreased angiogenesis in vivo." (PMID 26123362, 2015).
tumor (continued). "Within the current study, we confirm that treatment of cancer cell lines with the cMET inhibitor INC280 significantly impairs HGF-induced growth and motility of tumour cells, at least in part via inhibition of Akt, ERK and FAK phosphorylation." (PMID 25884642, 2015). "EMT is elicited by growth factors such as hepatocyte growth factor (HGF) secreted by tumor and stromal cells." (PMID 25543140, 2015). "In this review, we describe the specific types of cells in the tumor microenvironment that release HGF in order to promote the metastatic outgrowth through the activation of extracellular matrix remodeling, inflammation, migration, angiogenesis, and invasion." (PMID 28536400, 2015). "Tumor entities which are characterized by complex karyotypes were significantly more often HGF positive than entities with specific chromosomal aberrations (p<0.001, Chi Square and Fisher’s exact)." (PMID 25844809, 2015). "Stromal exosomes taken from cells deficient in TIMPs, harbour bioactive enzymes such as ADAM10 that support the generation of myofibroblasts with classical traits of tumour promotion including heightened HGF, SDF1 and other factors." (PMID 25596732, 2015). "Within cancer, the HGF/c-Met axis mediates a proliferative advantage and promotes tumor invasion and metastasis." (PMID 26000702, 2015). "The speed at which the tumours formed was dictated by the number of cells transplanted and was enhanced by use of supplements, particularly hyaluronans, HGF and VEGF." (PMID 26437858, 2015). "Hepatocyte growth factor (HGF) is one of the growth factors produced by CAF in tumor microenvironment and can bind its receptor of Met and activate the downstream phosphoinositide 3-kinase (PI3K)/AKT, which regulate chemoresistance and cell apoptosis." (PMID 26115510, 2015). "In the last years, it has been reported that one of the biologic activities exerted by HGF on tumor cells is up-regulating the expression of the pro-angiogenic factor VEGF." (PMID 26413215, 2015). "For example, tumor cells respond to Hepatocyte Growth Factor/Scatter Factor (HGF/SF, termed HGF hereafter for abbreviation)." (PMID 26337223, 2015). "Abnormal activation of the HGF/c-Met signaling pathway by aberrant hepsin overexpression is a possible mechanism for the enhancement of tumor progression." (PMID 26014348, 2015). "Third, VEGF works in concert with numerous signaling molecules such as angiopoietins, ephrins, hepatocyte growth factor, hypoxia-inducible factor, IL-6, and endostatin to promote tumor cell survival." (PMID 25810565, 2015). "In the majority of solid tumour types, HGF and its receptor, cMET, have been found to be over-expressed in cancer cells and tumour tissues." (PMID 26310485, 2015). "c-Met, a high-affinity receptor for Hepatocyte Growth Factor (HGF), plays a critical role in tumor growth, invasion, and metastasis." (PMID 26000702, 2015). "Consequences of dysregulated HGF and c-Met expression include tumor cell migration, proliferation, and protection from apoptosis." (PMID 26090722, 2015). "We focused on the secretion of EGF, HGF and IL6, because these soluble factors have been associated with an important role in tumor progression, resistance and inflammation." (PMID 26053043, 2015). "Growth factors such as HGF act in a complex way upon tumor cells: Increasing their motility and invasiveness, but also increasing their metabolism and energy consumption." (PMID 26337223, 2015). "The addition of the HGF neutralising antibody to the co-culture media proved to be effective in counteracting the fibroblast-elicited increase in tumor cell migration speed." (PMID 25880005, 2015). "Overall, the interconnected and diverse functions of the HGF/c-MET axis in driving tumor growth support the role of the microenvironment milieu in directing the metastatic spread of the primary tumor." (PMID 28536400, 2015).
tumor (continued). "HS20-treated spheroids had less phosphorylated c-Met, indicating that HS20 maintained the inhibitory effect on HGF activation in a 3D-tumor environment." (PMID 26332121, 2015). "The present study focused on the epigenetic modification and target tumor-suppressive genes of HGF treatment in HCC." (PMID 26099202, 2015). "Previous studies have shown that tumor stromal cells, such as fibroblasts, can secrete HGF that can promote the proliferation of cancer cells." (PMID 26115510, 2015). "Relatively high expression levels of FGF2, FGF7 and HGF are observed with fibroblasts established from tumor (HECAF2111) and three types of fibroblasts established from normal tissue (HFF75, HEF1173, and HEF2111)." (PMID 25884729, 2015). "HGF and its Met receptor are involved in the pathogenesis of KS whose biological features are compatible with the biological properties of HGF for invasive growth, tumour proliferation, and neovascularisation." (PMID 26296972, 2015). "Monocytes, macrophages and fibroblasts are thought to be the major sources of HGF in the tumor stroma." (PMID 25884419, 2015). "Consistent with our previous results, the HGF-autocrine tumor models U87M2 and U118 were sensitive to V-4084 in a dose-dependent manner, while DBM2 and U251M2 showed no response; SF295 cells showed modest sensitivity to V-4084." (PMID 26381735, 2015). "EGF and HGF showed to be effective rescue inducing growth factors in these tumor escape mechanisms acting via their RTKs resulting in increased cell survival and downstream signaling." (PMID 25799134, 2015). "Here, we found that HGF mRNA was predominantly expressed by CAFs and ECs while IL-6 mRNA was mainly expressed by tumor cells and by CAFs." (PMID 25849942, 2015). "Our study highlights the extensive importance of HGF present in the tumor micro-environment in bypassing the effects of RTK inhibitors." (PMID 26496080, 2015). "In pre-clinical models, rilotumumab was shown to inhibit tumor progression in a HGF/c-Met- dependent manner, and its tolerability was verified in early clinical trials." (PMID 25592281, 2015). "HGF and c-MET are key players in the tumor-stroma interactions, and HGF/c-MET signaling is strongly involved in tumor growth and progression, angiogenesis, and metastasis in many human cancers." (PMID 28536400, 2015). "HGF promotes the detachment of cancer cells from the primary tumor and their infiltration through the surrounding stroma favoring the pathways behind the degradation of the ECM." (PMID 28536400, 2015). "When looking at HGF expression, it is important to distinguish between autocrine signaling (HGF expression in the tumor cells) and paracrine signaling (HGF expression in stromal cells)." (PMID 25815459, 2015). "Other notable results from the study include reduced motility of endothelial cells, impaired tumor growth in response to HGF, and improved gemcitabine efficacy when used in combination with the frequently prescribed nucleoside inhibitor." (PMID 26404380, 2015). "We found that the combination of CPT-11 and anti-HGF antibody induced marked suppression of tumor development." (PMID 26090722, 2015). "c-Met and its ligand, HGF, are deregulated in many cancers and has been shown to be an important driver of primary tumor growth and metastasis." (PMID 25726528, 2015). "A number of novel therapeutic agents—either as therapeutic proteins or small molecules that target the HGF/MET pathway—have been tested in patients with different tumor types in clinical studies." (PMID 28536405, 2015). "Dong G finds that metastatic SCC cells that overexpress c-Met exhibit angiogenesis factor expression and enhance scattering in response to HGF in vitro, and tumorigenesis and metastasis in response to HGF in the tumor microenvironment in vivo." (PMID 25588551, 2015).